MYC (MYC proto-oncogene, bHLH transcription factor)
Diseases named in the same sentence as MYC in open-access papers (continued):
Sharing a sentence is not in itself a finding about the gene and the disease.
prostate carcinoma (continued). "Further multivariate Cox regression analysis was performed to select 6-gene prognostic signature (FADD, GABARAPL2, MYC, RAB24, RUBCN, and NPC1) and calculated the risk score of the prostate cancer patients." (PMID 33402116, 2021). "There is limited evidence showing induction of metabolic remodelling by individual oncogenes, such as MYC amplification, which promotes fatty acid synthesis and accelerates prostate cancer progression." (PMID 35127483, 2021). "In this way, it was shown that high OGT activity is essential for proliferation of prostate cancer cell that is driven by MYC." (PMID 33572160, 2021). "The proliferation inhibition activity of MYC inhibitor 361 (MYCi361) was more prominent in primary prostate cancer cells and patient-derived xenograft (PDX) model with higher level of circ_0057558." (PMID 33718387, 2021). "Many of the genes responsible for cell growth and proliferation are controlled by MYC, explaining the deregulation of this oncogene in the majority of malignancies, including prostate cancer." (PMID 35008216, 2021). "Previous studies have shown that the IRE1α–XBP1s pathway can promote the development of prostate cancer by activating c-MYC signaling." (PMID 34663798, 2021). "An interesting mechanism for regulating MYC oncogene expression was found in prostate cancer cell culture by switching the expression of three overlapping lncRNAs, NAT6531, NAT6558, and NAT7281." (PMID 34440124, 2021). "In prostate cancer cells, dysregulation of MYC expression was also found due to an increased level of ceRNA MYU, which is able to bind to miRNA miR-184." (PMID 34440124, 2021). "In particular, the somatic alteration from CACGCG to CACGTG created an E-box, the canonical binding motif for the oncogenic MYC protein, which is often deregulated in advanced prostate cancer patients." (PMID 34244513, 2021). "This study leveraged a gene-protein assay to assess MYC and PTEN status at prostate cancer biopsy and examined the association with adverse outcomes after surgery." (PMID 34062284, 2021). "MYC is a oncogenic transcription factor that plays a critical role in prostate cancer progression by influencing diverse molecular mechanisms." (PMID 33134178, 2020). "The OS-related prognostic model was constructed based on the five ARGs (FAM215A, FDD, MYC, RHEB, and ATG16L1) and significantly stratified prostate cancer patients into high- and low-risk groups in terms of OS (HR = 6.391, 95% CI = 1.581– 25.840, P < 0.001)." (PMID 32264916, 2020). "MYC upregulation is frequently observed in prostate cancer, and although targeting MYC remains a clinical challenge, preclinical studies have emphasized the potential efficacy of MYC blockade for patients with late-stage prostate cancer." (PMID 32630372, 2020). "Emerging shreds of evidence also showed that miR-33b negatively regulates MYC in osteosarcoma cancer and prostate cancer progression by directly binding with its 3′ UTR region." (PMID 33014831, 2020). "Let-7c was reported to function as tumor suppressor in prostate cancer by regulating AR transcription via MYC." (PMID 32974144, 2020). "In line with this notion, transcriptional silencing of MYC was shown as an effective strategy to block maintenance and proliferation of prostate cancer stem cells both in cell cultures and in tumor xenografts." (PMID 32722129, 2020). "Additional research is needed to replicate these findings and further investigate the potential role of MYC DNA methylation in aggressive prostate cancer using experimental laboratory designs." (PMID 33374332, 2020).
prostate carcinoma (continued). "High MYC expression in breast and prostate cancer cell lines, which mimics MYC amplification seen in a significant proportion of NSCLC tumors, leads to the transcriptional upregulation of prosaponin." (PMID 33014869, 2020). "AR signaling has also been shown to stimulate MYC in AR-driven prostate cancer, while in normal prostate tissue AR silences MYC to maintain normal homeostasis." (PMID 32630372, 2020). "Lipid-wise, the work from Loda and colleagues showed that MYC-overexpressing prostate cancer patients display higher activation of fatty acids turnover with respect to control patients, thus suggesting a role for MYC in this branch of cell metabolism." (PMID 32932943, 2020). "Using RNA-seq to profile a series of human prostate cancer specimens laser capture microdissected on the basis of MYC immunohistochemistry, MYC activity, and MEIS1 expression were inversely correlated." (PMID 32681068, 2020). "The WNT/APC/MYC signaling pathways play an important role in prostate development and prostate-cancer progression by mediating prostate stem/progenitor cell functions." (PMID 33318499, 2020). "In the last few years, an important body of work has demonstrated that PIM1 is an important partner of MYC function in prostate cancer and TNBC." (PMID 31570853, 2020). "Together, these chromatin-conformation data suggest that the rs72725854-harboring enhancer forms a spatial network with PCAT1, PRNCR1, PVT1, and MYC genes in 3D nuclear space in prostate cancer cells." (PMID 32680982, 2020). "Several of the affected genes were known to be associated with aggressive prostate cancer, such as loss of PTEN, CDH1 and BCAR1 and gain of MYC." (PMID 33255593, 2020). "PIM1, in turn, was shown to enhance the growth of lung adenocarcinoma by potentiating the c-MET signaling pathway and the growth of prostate carcinoma and triple-negative breast cancer in cooperation with MYC." (PMID 32504181, 2020). "MYC is commonly overexpressed in prostate tumor tissue and has long been thought to play a role in prostate cancer, and particularly with regard to prostate cancer progression." (PMID 33374332, 2020). "Previous research demonstrated the importance of MYC promoter methylation and signaling in the regulation of miR-27a-5p in prostate cancer, providing impetus for further study of MYC DNA methylation with regard to other genes/ncRNAs." (PMID 33374332, 2020). "Canonically, MYC up-regulation in luminal prostate cancer cells functions to oppose the terminally differentiating effects of AR." (PMID 32681068, 2020). "Here we show that the 8q24 prostate cancer rare variant, rs72725854 is present in an enhancer and regulates multiple lncRNAs genes namely, PCAT1, PRNCR1, PVT1, and proto-oncogene MYC in the region." (PMID 32680982, 2020). "Consistently, our recent study in prostate cancer cells demonstrates that XBP1s directly transactivates MYC expression." (PMID 32310340, 2020). "A subset of advanced prostate cancers also harbor amplified MYC, but it is distinct from the up-regulated MYC that is a hallmark of many localized prostate cancers." (PMID 32681068, 2020). "In this study, we found the up regulation of MYC proto oncogene in only poorly differentiated tumor of young prostate cancer men." (PMID 33575208, 2020). "For example, PERK‐eIF2α pathway is selectively activated in a mouse model of prostate cancer with MYC hyperactivation and is believed to hijack global protein synthesis required for cancer progression." (PMID 32310340, 2020). "Localized prostate cancer develops very slowly in most men, with the androgen receptor (AR) and MYC transcription factors amongst the most well-characterized drivers of prostate tumorigenesis." (PMID 32681068, 2020). "In human tumor samples, a high level of MYC in prostate cancer specifically leads to enhanced lipid metabolism." (PMID 31856871, 2019).
prostate carcinoma (continued). "This suggests that the enhancement of MYC-driven metabolic and epigenetic reprogramming may be a general mechanism that underlies the influence of dietary fat intake on prostate cancer progression although this hypothesis remains to be tested across prostate cancer molecular subtypes." (PMID 31554818, 2019). "CR cell lines from the C57BL/6 MYC driven prostate adenocarcinoma expressed markers of luminal epithelial lineage and provided a model for MYC-driven prostate cancer." (PMID 31717887, 2019). "Here the authors show that a diet high in saturated fats enhance the MYC-driven transcriptional program, a feature that independently predicts prostate cancer progression and death." (PMID 31554818, 2019). "Recent study of prostate cancer showed that HP1γ was upregulated by oncogenic c-MYC and HP1γ suppressed to expression of miR-451a in prostate cancer cells." (PMID 30813343, 2019). "Like ERβ, ZFHX3 also suppressed cell proliferation and MYC expression in prostate cancer cells, and downregulation of MYC was necessary for the suppressive effect of ZFHX3 on cell proliferation." (PMID 30979864, 2019). "Our experimental results showed that AICAR enhances the expression of TSC1 and TSC2, whereas it reduces the expression of mTOR and MYC as well as decreases the phosphorylation of p70S6K in 22Rv1 prostate cancer cells." (PMID 30987073, 2019). "We confirmed the prognostic value of the SFI-induced MYC signature in four independent clinical cohorts by analysing gene expression in the tumours from 631 prostate cancer patients." (PMID 31554818, 2019). "ERβ exerts its tumor suppressor role in prostate cancer cells by regulating gene transcription, including the inhibition of oncogenic MYC and CCND124,45,46." (PMID 30979864, 2019). "Results from immunoblot analysis showed that PGG treatment also reduced MYC expression in other human cancer cell lines, including PC-3 (prostate cancer) and HL-60 (leukemia)." (PMID 30760754, 2019). "Consistent with previous reports, the MYC pro-oncogene was found to as a central pathway node with the highest number of interacting genes which are inhibited by curcumin treatment in prostate cancer cells." (PMID 31581661, 2019). "While validating the suppressive activity of ERβ in AR-positive prostate cancer cells, these findings also indicate that downregulation of MYC also mediates ERβ’s tumor suppressor activity in AR-positive prostate cancer cells." (PMID 30979864, 2019). "Here, we provide the evidence that HFD acts as a master effector of prostate cancer metabolism, creating an environment that favours histone hypomethylation and results in an enhanced MYC-driven transcriptional program." (PMID 31554818, 2019). "The antagonistic relationship at the gene expression level was observed between AR and MYC in prostate cancer context." (PMID 31581661, 2019). "Among LNCaP, C4-2B, and PC-3 prostate cancer cell lines, MYC expression was apparently higher in C4-2B cells." (PMID 30979864, 2019). "The prostate cancer cells-derived large oncosomes (a new class of shedded vesicles) are endocytosed by fibroblasts, which activates Myc proto-oncogene protein (MYC) of recipient cells via active AKT1, giving these fibroblasts a protumor phenotype." (PMID 31355262, 2019). "MYC overexpression is a key driver of increased telomerase activity of prostate cancer cells, a conclusion supported by MYC gene overexpression in normal epithelial prostate cells or MYC knockdown in prostate cancer cells." (PMID 31366128, 2019). "Knocking-down of FOXP3 results in an elevated MYC expression in human prostate epithelial cells (HPECs), and reactivation of FOXP3 expression downregulates MYC expression in prostate cancer cell lines." (PMID 30863497, 2019).
prostate carcinoma (continued). "MYC is a well-established oncoprotein that plays a driving role in the development and progression of multiple types of cancers including prostate cancer." (PMID 30979864, 2019). "In two androgen receptor (AR)-positive prostate cancer cell lines, C4-2B and LNCaP, we first validated ERβ’s tumor suppressor activity indicated by the inhibition of cell proliferation and repression of MYC expression." (PMID 30979864, 2019). "MYC oncogene is frequently overexpressed in prostate tumors as a consequence of either somatic amplifications (8q24, advanced prostate cancers) or as consequence of deregulated expression (prostate intraepithelial neoplasia)." (PMID 31366128, 2019). "MYC transcript and protein levels were assessed in 198 PCa (primary prostate cancer) cases, 37 PIN (prostatic intraepithelial neoplasia) lesions and 10 MNPT (morphologically normal prostate tissue)." (PMID 29415999, 2018). "The deubiquitinating enzyme USP2 has been found to enhance MYC levels through the modulation of specific subsets of microRNAs in prostate cancer." (PMID 29511348, 2018). "PTEN genomic loss (leading to PI3K/AKT pathway activation) and 8q amplification (including the MYC gene) are the most frequent genetic alterations in human prostate cancer (~ 30%)." (PMID 29894516, 2018). "Specifically, this is the first study reporting the interplay between two independent mechanisms, aberrant promoter methylation and MYC signaling, in the regulation of miR-27a-5p in prostate cancer." (PMID 29415999, 2018). "In MYC-driven prostate cancer models, AZD1208 significantly decreased tumour growth, an effect that was accompanied by decreased cellular proliferation and increased rates of apoptosis." (PMID 29765150, 2018). "Further, concurrent copy number gain of MYC and loss of PTEN is associated with prostate cancer-specific mortality, reported in 57% of metastatic tumors compared to 9.6% in localized disease." (PMID 29686284, 2018). "The c-MYC onco-protein is a transcription factor, which upregulation is a prevalent and early change in prostate cancer and therefore considered a critical oncogenic event." (PMID 29212195, 2017). "Recent evidence demonstrated the efficacy of targeting ribosome biogenesis with the specific inhibitor of ribosomal RNA synthesis, CX-5461 in v-myc avian myelocytomatosis viral oncogene homolog (MYC)-driven haematological and prostate cancers." (PMID 28117679, 2017). "For example, ETV4 directly regulates MYC and other proliferation genes in prostate cancer cell lines." (PMID 29371979, 2017). "For example, gene amplification of the c-MYC locus is one of the most representative gene abnormalities in prostate cancer." (PMID 28590415, 2017). "Presumably, of the various factors which lead to c-MYC gene amplification in prostate cancer, increased expression and activity of AR can increase c-Myc expression, which is a direct downstream target of AR33." (PMID 28852180, 2017). "Deregulation of MYC has long been recognized as playing a role in human malignancies, including lung, breast, colon, and prostate cancers, Burkitt’s lymphoma and other hematological malignancies." (PMID 28192473, 2017). "Our approach has yielded 11 transcription factors that show strong cancer-specific transcriptional activation of targets, including the novel candidates KAT2A and TRIM28, alongside established drivers of prostate cancer MYC, ETS1, GABP and YY1." (PMID 28592290, 2017).
prostate carcinoma (continued). "In prostate cancer, a capture Hi-C experiment revealed that some high-risk SNPs interact with their long-distance target genes, including CAPG, C2orf43, RFX6, NFASC, MYC and AGAP7P, through chromosome loops." (PMID 29149895, 2017). "PCAT1 was shown to increase cell proliferation of prostate cancer cells by regulating MYC protein at the post-transcriptional level by interfering with miR-34, a miRNA known to target MYC 3′UTR and regulate MYC translation." (PMID 28704924, 2017). "Paradoxically, it is well known that the abundance of MYC oncoprotein closely correlates with chemoresistance in many tumor types, including prostate cancer, ovarian cancer, melanoma, lung cancer, and hepatocellular carcinoma both in vitro and in vivo." (PMID 28590415, 2017). "We also included as biological controls several genes known to be important for prostate cancer cell viability: AR, MYC, and KIF11." (PMID 29340039, 2017). "Benign human prostate organoids were transduced with lentiviruses expressing MYC, shPTEN, shTP53 and AR, alone and in various combinations, to recapitulate prostate cancer development." (PMID 28881646, 2017). "We show that inhibition of OGT activity inhibits the proliferation of prostate cancer cells, leads to sustained loss of c-MYC and suppresses the expression of CDK1, elevated expression of which predicts prostate cancer recurrence (p=0.00179)." (PMID 26824323, 2016). "Based on these data, we decided to analyse the possible metabolic adaptations that enable prostate cancer cell survival despite the significant down-regulation of prominent prostate cancer oncogenes, c-MYC and AR." (PMID 26824323, 2016). "This discrepancy indicates a possible uncoupling of the mechanisms of down regulation of miR-17-92a miRNA cluster and expression of c-MYC in prostate cancer cells." (PMID 27650539, 2016). "Chromosome aneusomy, including the gain of the 8q24 (MYC) region, has been reported from radical prostatectomy specimens (both carcinoma and adjacent tissues) in those with prostate cancer as well as from 15% of benign prostatic hyperplasia tissue." (PMID 26966665, 2016). "Studies shown that the chromosome 8q24 region is related to the occurrence of prostate cancer and colon cancer, which can play a role in carcinogenesis through interacting with MYC gene amplification and over expression." (PMID 27634905, 2016). "Despite this, expression of c-MYC in early prostatic cancer tissues has been shown to be a good indicator for aggressive disease." (PMID 26966665, 2016). "Recent studies have shown that metformin has an ability to reduce MYC protein level in vivo and in vitro in several types of cancer, including lung cancer and prostate cancer." (PMID 26083494, 2015). "In this study, we also showed that ERα is highly expressed in two different mouse models of aggressive prostate cancer, PTEN-deficient and Hi-MYC mice, mirroring human disease." (PMID 25436982, 2015). "MYC was also up-regulated in this dataset and the overexpression (gene amplification, mRNA, and protein increase) of MYC in prostate cancer is well-documented." (PMID 26683658, 2015). "c-MYC is also located at 8q24, a known regulator of cell growth, and has a critical role in prostate cancer development and progression." (PMID 25638161, 2015). "We analyzed the phosphorylation of c-MYC at T58 and observed marked increase in two prostate cancer cell lines after SIRT3 overexpression." (PMID 26317998, 2015). "In a study of prostate cancer, the c-MYC GCN gain included the criterion of a c-MYC/CEP8 ratio > 1.5, and a poor prognosis was observed for patients in this category." (PMID 26426996, 2015).